EGFR (epidermal growth factor receptor)
Diseases named in the same sentence as EGFR in open-access papers (continued):
Sharing a sentence is not in itself a finding about the gene and the disease.
adenocarcinoma (continued). "The EGFR mutations in NSCLC are primarily found in patients with adenocarcinoma, non-smokers, and females." (PMID 33906297, 2021). "The incidence of epidermal growth factor receptor (EGFR) mutations in the Caucasian population is approximately 10%, but is higher among never-smokers, patients with adenocarcinoma, females, and individuals from East Asia." (PMID 33867871, 2021). "In another word, EGFR 19-del mutation had an increased frequency in female, nonsmokers, who had family history and adenocarcinoma patients." (PMID 32047821, 2020). "Another study of 524 patients with NSCLC also found that the rate of EGFR mutation vary with smoking status and histological subtypes, EGFR being the most frequently altered gene in nonsmoking adenocarcinoma patients." (PMID 32657049, 2020). "The mutations most frequently reported in adenocarcinoma occur in the KRAS and EGFR genes." (PMID 32756609, 2020). "ALK gene aberrations are more common in the adenocarcinoma histological subtype, in never or light smoker young women and are considered to be largely mutually exclusive with genetic mutations in the epidermal growth factor receptor (EGFR) and KRAS." (PMID 33352844, 2020). "Among Asian populations, the average incidences of EGFR mutations were 31% overall, 47% among patients with adenocarcinoma, and 56% among nonsmokers." (PMID 32762742, 2020). "EGFR mutations tend to be more common among patients with an adenocarcinoma histology and among nonsmokers." (PMID 32762742, 2020). "The purpose of this study was to investigate the differences in CT characteristics and disease spread patterns between ROS1-rearranged adenocarcinomas and epidermal growth factor receptor (EGFR)-mutant or anaplastic lymphoma kinase (ALK)-rearranged adenocarcinomas." (PMID 33005033, 2020). "The clinical characteristics of patients with EGFR e20ins are similar to those with EGFR classic mutations, which are more prevalent in females, nonsmokers, and tumors with adenocarcinoma histology." (PMID 32412152, 2020). "Ten patients had EGFR-mutated and one had ALK-rearrangement adenocarcinomas." (PMID 33228799, 2020). "Furthermore, in a subgroup analysis of stage IV adenocarcinoma, the pSUVmax wasn't meaningful between different EGFR status." (PMID 32742498, 2020). "Moreover, we also observed concurrent mutations of EGFR L858R and ERBB2 S310F in two adenocarcinoma patients; EGFR L858R and ERBB2 amplification in three LUAD patients." (PMID 31692283, 2020). "EGFR and KRAS mutations in tissue was detected only in adenocarcinomas." (PMID 32196518, 2020). "EGFR exon 19 deletion was identified in both the adenocarcinoma and LCNEC." (PMID 32762742, 2020). "EGFR gene mutations were associated with several characteristics such as mutations more frequently in female patients, adenocarcinoma type NSCLC, non-smokers/those who had quit smoking and East Asian patients." (PMID 32283582, 2020). "This is because NSCLC adenocarcinoma samples were screened for EGFR beforehand." (PMID 33425389, 2020). "The high expression of miR-34 was found as predictive marker in M1b metastasis, adenocarcinoma cell type and adenocarcinoma negative EGFR mutation in the advanced stage NSCLC." (PMID 32283582, 2020). "However, further analysis of the detailed subtypes revealed that among all the subtypes, invasive lepidic adenocarcinoma had the most EGFR‐mutant patients (P = 0.003), followed by acinar and micropapillary subtypes." (PMID 31692283, 2020). "High miR-34 expression in advanced stage NSCLC is the predictive factor for multiple metastatic, adenocarcinoma cell type and adenocarcinoma negative EGFR mutation." (PMID 32283582, 2020). "The most frequent histological type was adenocarcinoma (76%) and Epidermal Growth Factor Receptor (EGFR) activating mutations were found in 9% of patients while no Anaplastic Lymphoma Kinase (ALK) translocations were detected." (PMID 32983959, 2020).
adenocarcinoma (continued). "In Asia, the most common gene mutation in adenocarcinoma patients is EGFR, and most of EGFR mutations occur in never smoker." (PMID 32657049, 2020). "Furthermore, the amount of EGFR mutations was higher in adenocarcinoma (64.1% vs 34.1%, P < 0.001) than in NSCC, favor adenocarcinoma." (PMID 32429938, 2020). "Among white populations, the average incidences of EGFR mutations were 7% overall, 13% among patients with adenocarcinoma, and 35% among nonsmokers." (PMID 32762742, 2020). "Clinical features in patients with NSCLC are also non-negligible variables in the evaluation of EGFR mutations, which are more likely to occur in Asians, adenocarcinomas, females, and nonsmokers." (PMID 33134170, 2020). "This study shows that EML4-ALK rearrangement gene has high prevalence in selected adenocarcinoma and EGFR mutation-negative populations." (PMID 33425389, 2020). "The 6 participants with the EGFR-activating mutation had a significantly better the median OS (39 months) than the 20 participants with the EGFR wild-type or non-adenocarcinoma (20 months) without significant difference." (PMID 32563259, 2020). "These patterns (I and II) were distinguished by a significantly higher EGFR mutation rate (p < 0.001), proportion of females (p < 0.001), adenocarcinomas (p < 0.001), and never smokers (p < 0.001) in pattern II for both the training and validation cohorts." (PMID 33067442, 2020). "Gene sequencing has identified EGFR mutations in East Asians never smokers, and women having adenocarcinomas." (PMID 32622356, 2020). "We speculate that EGFR silence in LuCSCs contributes to the failure of NSCLC mono-therapy, even though adenocarcinomas are driven by overexpressed, mutant or wild type EGFR." (PMID 31069016, 2019). "Moreover, research on the prognosis of patients with TTF-1–negative, EGFR-positive adenocarcinoma is also limited." (PMID 31196060, 2019). "The optimal cut-off point for differentiating adenocarcinomas with EGFR mutation from adenocarcinomas without EGFR mutation was 34.3%, with values above this threshold being likely to represent adenocarcinomas with EGFR mutation." (PMID 30956990, 2019). "Five patients had EGFR mutation-positive and TTF-1-negative adenocarcinoma." (PMID 31196060, 2019). "However, a meta-analysis demonstrated that there were significantly increased odds of presenting the EGFR and ALK-EML4 mutations in adenocarcinomas compared to NSCLC44." (PMID 31148582, 2019). "In addition, H1975 is a human adenocarcinoma cell line with EGFRL858R/T790M mutation and FGFR1 expression, which can be used as an EGFR-TKI acquired resistant cell line." (PMID 31998131, 2019). "The optimal cut-off point for differentiating adenocarcinomas with exon 21 missense mutations from adenocarcinomas without EGFR mutation was 37.7%, with values above this threshold being likely to represent adenocarcinomas with exon 21 missense mutations." (PMID 30956990, 2019). "All of these indicated that AM could improve the short-term effect of EGFR-TKI resistant adenocarcinoma patients." (PMID 31570733, 2019). "In this study, we monitored EGFR mutations in serial plasma samples of Adenocarcinoma patients treated with EGFR TKI and shown a negative result of patients who still archived partial response or stable disease." (PMID 30661185, 2019). "EGFR mutations are more frequent in tumors with adenocarcinoma histology, in never-smokers or light smokers of tobacco, in women with NSCLC, and in patients with East Asian ethnicities." (PMID 31088573, 2019). "Among the 108 patients with adenocarcinoma, 70 had mutant EGFR." (PMID 31450665, 2019). "Given the emerging critical roles of CD47 and CRT in NSCLC adenocarcinomas, in the present study, we assessed whether the EGFR TKI gefitinib modulates their expression in different EGFR-mutated NSCLCs." (PMID 32082304, 2019). "Next, we examined whether endogenous EGFR signaling plays a role in mediating the invasive behavior of poorly differentiated adenocarcinoma progeny." (PMID 31069016, 2019).
adenocarcinoma (continued). "Among the unselected adenocarcinoma patients, EGFR and ERBB2 mutations and ALK fusions were frequent in nonsmoking female patients." (PMID 31387567, 2019). "Most adenocarcinomas expressed MUC21 (if tumors with very focal expression were included, a positive frequency, for example MUC21 expression detected by the polyclonal antibody, was 77.6% (187/241) of whole LADCs, and 87.1% (101/116) of EGFR-mutated LADCs)." (PMID 30973916, 2019). "Several studies emphasized that the frequency of EGFR mutation increased with several clinicopathologic factors, including adenocarcinoma, never smoker and being female." (PMID 31336878, 2019). "Of 785 adenocarcinomas, all the patients had their EGFR and ALK status identified." (PMID 31561631, 2019). "Adenocarcinoma with KRAS mutation that is considered a subgroup of CRC show a negative treatment response to epidermal growth factor receptor (EGFR)-targeted antibodies." (PMID 31727020, 2019). "In our study, five patients had EGFR mutation-positive and TTF-1-negative adenocarcinoma." (PMID 31196060, 2019). "In conclusion, our results showed that GGO volume percentage in adenocarcinoma with EGFR mutation was significantly higher than that in adenocarcinoma without EGFR mutation." (PMID 30956990, 2019). "EGFR mutations are observed mainly in non-smoker females with adenocarcinoma showing a lepidic growing pattern and also in atypical adenomatous hyperplasia (AAH) of the lung." (PMID 31867335, 2019). "Studies in Korea and Japan have described characteristics that are similar to those of patients with an EGFR mutation, regardless of the mutation: female gender, < 65 years of age, never-smoker of tobacco, and adenocarcinoma histology." (PMID 31088573, 2019). "In our study, patients with EGFR double mutations were more likely to be nonsmokers, have PS 0-1, have adenocarcinoma, and be at stage III-IV." (PMID 29581983, 2018). "Analysis of SCLC tumors utilizing patient tumors and mouse models suggest that the SCLC phenotype can be developed due to transformation or trans-differentiation of NSCLC adenocarcinoma, as a result of RB1 inactivation and/or loss of EGFR expression, as recently reviewed extensively." (PMID 29600194, 2018). "It is predominantly detected in adenocarcinomas of light smokers (< 10 packs per year) or non-smokers at a younger age, and is independent of epidermal growth factor receptor (EGFR) or KRAS mutations." (PMID 29304828, 2018). "In pulmonary carcinomas, EGFR mutation is associated with Asians, females, non-smokers, and the adenocarcinoma type, and it has become evident that EGFR tyrosine kinase inhibitors are highly effective for pulmonary adenocarcinomas with EGFR mutations." (PMID 29682203, 2018). "In addition, we examined several EGFR wild type cell adenocarcinoma cell lines as well, and again observed this effect (suggesting that it is not selective for SCC)." (PMID 29581842, 2018). "As expected for patients carrying EGFR mutations and in line with previous reports in Caucasians, we found a population with a high proportion of females, never-smoker patients, and adenocarcinoma histology." (PMID 29382302, 2018). "EGFR-mutated adenocarcinoma is characterized by East-Asian ethnicity, female gender, non/light-smoking history, and hobnail cell morphology." (PMID 29690599, 2018). "EGFR mutations were found more frequently in females, non-smokers, adenocarcinomas and stage I disease." (PMID 29164298, 2018).
adenocarcinoma (continued). "It has also been shown that serum level of SP-D reflects its levels in the lung and that higher amount of SP-D in the serum correlated with better overall survival in patients with EGFR mutant adenocarcinoma undergoing treatment with gefitinib, a tyrosine kinase inhibitor." (PMID 30127783, 2018). "Our data also showed that B7-H3-positive adenocarcinomas harbor EGFR mutations significantly less frequently, suggesting a non-redundant biological role of the two targets: EGFR and B7-H3." (PMID 30513627, 2018). "East Asians, females, never-smokers and patients with adenocarcinoma histology, who are associated with a higher incidence of EGFR activating mutations, have been shown to derive a greater clinical benefit from EGFR TKIs." (PMID 29382302, 2018). "ALK rearrangement is more commonly found in younger patients with adenocarcinoma histology who are light smokers or who have never smoked, and they are almost always mutually exclusive with other oncogenic drivers such as EGFR mutations." (PMID 29914100, 2018). "Among all patients with adenocarcinoma, patient had neither an epidermal growth factor receptor mutation and the echinoderm microtubule-associated protein-like 4-anaplastic lymphoma kinase (EML4-ALK) fusion gene." (PMID 30190787, 2018). "The Epidermal Growth Factor Receptor(EGFR), a transmembrane glycoprotein, is mutated in approximately 10–15%of European patients, more frequently in women, adenocarcinoma type and never-smokers." (PMID 29545937, 2018). "Most centers reported that adenocarcinomas and NSCLC-NOS were tested for activating EGFR mutations." (PMID 29523116, 2018). "Multivariate analysis demonstrated that pSUVmax < 7.0, female sex, non-smoker status and adenocarcinoma were predictors of EGFR mutations." (PMID 29164298, 2018). "Therefore, we aimed to determine if the radiomic features on CT images at baseline and first follow-up, or the percentage change between baseline and first follow-up, can predict PFS in EGFR-mutant adenocarcinoma patients treated with first-line EGFR TKIs." (PMID 29099855, 2017). "In our study, a univariate analysis showed that specific characteristics (female, non-smoking, PS 0–1, adenocarcinoma, recurrent disease, EGFR mutations, receiving EGFR-TKI therapy) predicted a better survival outcome." (PMID 28079142, 2017). "The EGFR gene mutation rate detected in our study for all patients (46.5%) and for patients with adenocarcinoma histological subtype (47.6%) were similar to those reported previously for Chinese patients with NSCLC of adenocarcinoma histology (40.3–64.5%)." (PMID 28673332, 2017). "EGFR 19 del and 21L858R mutations are the most common sensitive mutations of EGFR, which most commonly found in tumors in women, patients with adenocarcinoma, never or light former smokers, and patients of east-Asian origin." (PMID 28903458, 2017). "In plasma subgroup, we found female (p < 0.001), no smoking (p = 0.01) and adenocarcinoma (p = 0.042) was associated with higher EGFR mutation rates." (PMID 28107191, 2017). "EGFR and KRAS mutations were simultaneously found in 16.7% and 33.3% of HER2-overexpressing adenocarcinomas, respectively, as well as in 52.2% and 6.5% of HER2-amplified adenocarcinomas, respectively." (PMID 28146588, 2017). "However, the role of anti-EGFR therapy is controversial in patients with adenocarcinoma of the esophagus or stomach." (PMID 29228748, 2017). "In the ISEL trial, before the identification of EGFR gene mutation, researchers found that gefitinib achieved better survival in female, nonsmoker patients with adenocarcinoma." (PMID 28203260, 2017). "In two patients with adenocarcinoma of the lung driver mutations were detected (EGFR Exon 19 deletion and ALK rearrangement) out of the lymph node metastasis." (PMID 28693444, 2017).
adenocarcinoma (continued). "The most common EGFR mutations have been shown to be found in adenocarcinoma in female non-smoker of East Asian ethnicity, and the mutation rate is reported to be 27–56% in this population compared with 8–10% worldwide." (PMID 28068946, 2017). "Patients with EGFR-mutant adenocarcinoma and BM treated with icotinib exhibited prolonged survival." (PMID 28332624, 2017). "Previous studies have demonstrated that EGFR mutations are strongly correlated with clinical features, including Asian, female, non-smokers and adenocarcinoma." (PMID 29246019, 2017). "A549 cells and HCC827 cells belong to adenocarcinoma, especially, that HCC827 had deletional mutations (E746-A750) in EGFR exon 19 which is different from other cell lines that could help us to discuss the importance of EGFR." (PMID 28915650, 2017). "We have demonstrated that the incorporation of radiomic features along with conventional clinical factors was superior to the performance of clinical-factors alone model in prediction of PFS in EGFR-mutant adenocarcinoma patients treated with first-line EGFR TKIs." (PMID 29099855, 2017). "It seemed that female (p < 0.0001), no smoking (p = 0.001), adenocarcinoma (p < 0.0001), and tissue specimen (p = 0.026) were associated with higher EGFR mutation." (PMID 28107191, 2017). "Four clinical features are associated with higher probability of EGFR mutation: never-smoker, adenocarcinoma, female and Asian descent." (PMID 29232915, 2017). "EGFR mutations have been linked patients with adenocarcinoma, lack of prior smoking history, females, and Asians." (PMID 28881771, 2017). "Quinalizarin also had variable effects in a panel of cell adenocarcinoma lines with or without EGFR mutations." (PMID 28134850, 2017). "EGFR mutation is more common in certain patient subpopulation, including adenocarcinoma, East Asian ethnicity, females and never smokers; also these subjects tend to respond better to EGFR-TKIs22." (PMID 28814805, 2017). "Among 115 adenocarcinoma cases, only 38 harbored a KRAS mutation, and 73 had an EGFR mutation." (PMID 28460455, 2017). "Considering the adenocarcinomas without any actionable EGFR or BRAF mutations, the percentage of tumors exhibiting MET exon 14 splice mutations was eight out of 100 patients." (PMID 28418914, 2017). "Adenocarcinomas with a micropapillary pattern have a higher frequency of EGFR mutations than adenocarcinomas without this pattern." (PMID 28894699, 2017). "However, we should remind the differences between adenocarcinomas of the colon-rectum and of the lung as regard the activation of EGFR." (PMID 29088281, 2017). "We found female (p < 0.0001), no smoking (p = 0.001), adenocarcinoma (p < 0.0001), and tissue specimen (p = 0.026) were associated with higher EGFR mutation rate." (PMID 28107191, 2017). "In tissue subgroups, younger age (< 65 year) (p < 0.001), female (p < 0.001), no smoking status (p < 0.001), and adenocarcinoma (p < 0.001) was correlated with higher EGFR mutation rate." (PMID 28107191, 2017). "We found that re-treated with EGFR-TKIs were not inferior to traditional cytotoxic chemotherapy if they were selected as the third-line therapy in initial EGFR-mutated adenocarcinoma patients." (PMID 28486985, 2017). "Detailed pathologic examination of the ERβ-positive adenocarcinoma may be necessary to show the genotype-phenotype correlations, similar to those found in the ALK-rearranged or the EGFR-mutated adenocarcinoma." (PMID 28783064, 2017). "EGFR signaling was able to drive alveolar type II cells to differentiate into adenocarcinoma, while EGFR-TKIs could block this process." (PMID 29163853, 2017). "Patients with adenocarcinoma histology, females, never-smokers, and those of Asian ethnicity are more likely to have EGFR mutations and thus exhibit better responses to EGFR tyrosine kinase inhibitors (TKIs)." (PMID 28422710, 2017).